MIR196B (microRNA 196b)
Synonyms: hsa-mir-196b; MIRN196B; miR-196b; miRNA196B
Gene: MicroRNA gene on chromosome 7 (27,169,480 to 27,169,563, reverse strand). Ensembl gene ENSG00000283745.
Gene Ontology:
Biological process: miRNA-mediated post-transcriptional gene silencing
Cellular component: RISC complex
Homologues: Orthologues: chimpanzee ptr-mir-196b (100% identical), dog MIR196B (100% identical), guinea pig MIR196B (100% identical), macaque MIR196B (100% identical), mouse Mir196b (100% identical), pig ssc-mir-196b-1 (100% identical), rabbit MIR196B (100% identical). Paralogues in human: MIR196A2 (75% identical), MIR196A1 (52% identical).
Diseases named in the same sentence as MIR196B in open-access papers:
MIR196B is named in the same sentence as 4 diseases in open-access papers, as found by Europe PMC text mining. Sharing a sentence is not in itself a finding about the gene and the disease. The quoted sentences say what the papers report.
colorectal cancer (2 papers, 2015 to 2025). A primary or metastatic malignant neoplasm that affects the colon or rectum. "MIR196B expression was up-regulated in colorectal cancer tissue, whereas FAS expression was down-regulated." (PMID 25605245, 2015). "We selected one, MIR196B, which was up-regulated in human colorectal cancer tissue, for further investigation in this study." (PMID 25605245, 2015). "We used mRNA microarray analysis and bioinformatics tools to identify MIR196B target genes in colorectal cancer." (PMID 25605245, 2015). "mRNA microarray expression profiles of MIR196B-overexpressing colorectal cancer cell lines were generated to identify MIR196B target molecules." (PMID 25605245, 2015). "Therefore, our results suggest that anti-MIR196B is a candidate material for anticancer therapy in human colorectal cancer." (PMID 25605245, 2015). "Our results suggest that up-regulated MIR196B modulates apoptosis in colorectal cancer cells by partially repressing FAS expression and that anti-MIR196B could be useful as an anti-cancer drug in colorectal cancer." (PMID 25605245, 2015). "Our results suggest that the up-regulation of MIR196B modulates apoptosis in colorectal cancer cells by partially repressing FAS expression and that anti-MIR196B could be a potential candidate as an anti-cancer drug in colorectal cancer therapy." (PMID 25605245, 2015). "And these results highlighted the upregulation of MIR196B in CRC tissues, which regulates the expression levels of GLTP during the colorectal cancer (CRC) development process." (PMID 39898245, 2025). "In contrast, anti-MIR196B up-regulated FAS expression and increased apoptosis in colorectal cancer cell lines." (PMID 25605245, 2015). "Furthermore, anti-MIR196B up-regulated FAS expression and increased apoptosis in colorectal cancer cell lines." (PMID 25605245, 2015).
colon cancer (1 paper, 2015). "The result showed that the overexpression of anti-MIR196B up-regulated the 5-FU induced apoptosis in colon cancer cells." (PMID 25605245, 2015). "We chose MIR196B, which was specifically up-regulated in colon cancer, for further study." (PMID 25605245, 2015). "So, FAS expression might be depend on endogenous MIR196B expression in colon cancer cell lines." (PMID 25605245, 2015).
MIR196B also shares sentences with these, for which no sentence is quoted: cancer (1 paper); pancreatic adenocarcinoma (1).